NFATC1 (nuclear factor of activated T cells 1)
Diseases named in the same sentence as NFATC1 in open-access papers (continued):
Sharing a sentence is not in itself a finding about the gene and the disease.
breast cancer (40 papers, 2012 to 2025). A primary or metastatic malignant neoplasm involving the breast. "Dynamic imbalance of DNMT is linked to atherosclerosis through CD137/NFATc1 signaling, and is implicated in many kinds of carcinoma, including breast cancer, liver cancer, and thyroid cancer." (PMID 40405297, 2025). "The activity of hypericin on osteoclasts and breast cancer-mediated osteoclastogenesis was associated with the inhibition of NFATc1 signaling pathway and attenuation of Ca2+ oscillation." (PMID 29416737, 2018). "Nuclear factor of activated T cells 1 (NFAT1) expression has been associated with increased migratory/invasive properties of mammary tumor-derived cell lines in vitro." (PMID 25719243, 2015). "Our findings suggest that TP inhibits NF-κB and ERK signaling pathways, reduces breast cancer-induced osteoclastogenesis, and decreases NFATc1, CTSK, and RANKL expression." (PMID 40444046, 2025). "One study showed that breast cancer cells upregulate the production of miR-21, an upregulator of nuclear factor of activated T cell 1 (NFATc1)." (PMID 40722712, 2025). "Since NFATc1 is involved in mammary epithelial morphogenesis, inhibiting NFATc1 reduced basal-like breast cancer cells' aggressiveness and therapy resistance." (PMID 39822413, 2024). "It has also been shown that NFATc1 activation promotes liver cancer cell proliferation and breast cancer cell migration." (PMID 25638160, 2015). "The identified down-regulated genes in the early recurrence group, e.g., NFATC1, participate in the immune system, which may indicate the role of immune system in breast cancer recurrence." (PMID 39888956, 2025). "Furthermore, elevated SREBP2 expression is induced by CREB signaling, which subsequently upregulates NFATc1 expression required for mature osteoclast formation, contributing critically to breast cancer invasion and bone metastasis." (PMID 40308757, 2025). "Moreover, RCAN1.4 was identified as a super suppressor of breast cancer and a potential therapeutic target for late-stage breast cancer patients with bone and brain lesions by ablation of calcineurin/NFATc1 signaling." (PMID 36071984, 2022). "In addition, calcineurin/NFATc1 signaling promotes breast cancer metastasis to bone and brain and upregulates IGFI." (PMID 36071984, 2022). "Like Nfatc1, Nfatc2 also promotes breast cancer cell invasion and metastasis." (PMID 34932179, 2021). "Nfatc1 is also required for breast cancer cell migration and invasion in vitro as well as tumorigenesis and metastasis in vivo, and its expression is upregulated in breast cancer." (PMID 34932179, 2021). "High levels of NFATc1 expression in breast cancer correlate with poor prognosis." (PMID 34932179, 2021). "Our results showed that RCAN1.4 may be an endogenous tumour suppressor of breast cancer and that it played a critical role in the progression and metastasis of breast cancer by blocking CaN/NFATc1 signalling." (PMID 32771023, 2020). "The malignancy depended on calcineurin-mediated NFATc1 nuclear localization in breast cancer cells." (PMID 32771023, 2020). "In addition, we have previously shown that breast cancer cells produce factors capable of inducing calcium signaling and maintaining NFATc1 activation in RANKL-primed osteoclast precursors." (PMID 24370273, 2013). "Since NFATc1 is a calcium-dependent osteoclastogenic transcription factor, highly up-regulated during osteoclast formation, and involved in breast cancer-induced osteoclastogenesis; we next examined if NFATc1 mediates the osteoclastogenic effects of prostate cancer CM." (PMID 24370273, 2013). "The functional involvement of Nfatc1 in normal mammary basal stem/progenitor cells raises the possibility that NFATc1 may also regulate the activity of malignant stem/progenitor cells in breast cancer, a notion worth testing in the future." (PMID 34932179, 2021). "In breast cancer, HYP has been shown to inhibit bone metastases by targeting osteoclast activity via the NFATc1 signaling pathway." (PMID 41226910, 2025).
breast cancer (continued). "NFATC1 binds to the ITGB3 promoter in osteoclast precursor cells, while NFATC2 and NFAT5 promote ITGA6/ITGB4-mediated cell invasion in breast cancer." (PMID 31730483, 2019). "An analogous signalling was proposed in the TCDD study, a dioxin which actually exhibits pancreatic carcinogenic activity, and which stimulated migration via calcineurin, NFATc1 and ATX induction in breast cancer cells." (PMID 22952646, 2012). "Recently, the expression of FUN14 domain-containing protein 1 was positively correlated with breast cancer metastasis and the Ca2+/NFATC1/BMI1 axis, suggesting that inhibition of this protein could represent a therapeutic target for breast cancer." (PMID 33511135, 2020). "In particular, NFATc1 was shown to promote tumor growth via, for instance, induction of c-myc in pancreatic cancer, cyclooxygenase (COX)-2 in melanoma, and autotaxin/lysophosphatidic acid axis in breast cancer." (PMID 25638160, 2015). "Furthermore, FUNDC1-involved MAMs can promote calcium transport to cytoplasm, making nuclear factor of activated T cells 1 (NFATC1) dephosphorylated, and then Bmi1 polycomb ring finger oncogene (BMI1) is upregulated, thus promoting the progression of breast cancer." (PMID 35959490, 2022). "However, in breast cancer, FUNDC1 likely functions as a tumor promoter through different mechanisms, in which depletion of FUNDC1 blocks TNBC cell proliferation by deregulating Ca2+ release from the ER and through NFATC1 activation, which are reversed by overexpression of BMI1." (PMID 36831455, 2023).
osteopetrosis (29 papers, 2014 to 2025). Osteopetrosis, also known as marble bone disease, is a descriptive term that refers to a group of rare, heritable disorders of the skeleton characterized by increased bone density on radiographs. "Another report states that osteoclast‐specific conditional NFATc1‐deficient mice develop osteopetrosis due to impaired osteoclastogenesis." (PMID 35781786, 2022). "Previous study has reported that NFATc1-deficiency in osteoclast precursor cells cannot differentiate into osteoclasts, and NFATc1-knockout mice exhibits a serious osteopetrosis because of the increase of bone mass." (PMID 34136493, 2021). "Secondly, NFATc1 regulates the expression of target genes and proteins that empower osteoclastic resorption as evidenced by the osteopetrosis in the conditional NFATc1-deficient mice." (PMID 34630071, 2021). "NFATc1 is a key transcription factor in osteoclastogenesis and report had stated that osteoclast-specific conditional NFATc1-deficient mice developed osteopetrosis due to the defective of osteoclastogenesis." (PMID 33574753, 2020). "Other studies have demonstrated that NFATc1 deficiency causes osteopetrosis, indicating that NFATc1 is a crucial factor for osteoclast differentiation." (PMID 32024503, 2020). "NFATc1-deficient mice develop osteopetrosis due to impaired osteoclastogenesis but its ectopic expression in osteoclast precursor cells induces osteoclasts differentiation without RANKL." (PMID 31555218, 2019). "c-fos or NFATc-1 deficient mice exhibit osteopetrosis due to deficiency of osteoclast differentiation." (PMID 30915145, 2019). "The deficiency of NFATc1 causes impaired osteoclastogenesis and osteopetrosis in vivo." (PMID 40765418, 2025). "Additionally, NFATc1-deficient mice develop osteopetrosis due to impaired osteoclast formation, and NFATc1 ectopic expression can induce osteoclast differentiation even in the absence of RANKL." (PMID 36297038, 2022). "The loss of c-Fos or NFATc1 results in severe osteopetrosis in mice." (PMID 35602099, 2022). "Similarly, deficiency of c-Fos abrogates NFATc1 induction and osteoclastogenesis in vitro and results in marked osteopetrosis in vivo, while overexpression of c-Fos can rescue NFATc1 expression in p50/p52 deficient cells." (PMID 33912557, 2021). "The NFATc1 deficient mice exhibits impaired osteoclastogenesis and severe osteopetrosis." (PMID 34136493, 2021). "NFATc1-deficient mice have defects of osteoclastogenesis and also show symptoms of osteopetrosis." (PMID 28955231, 2017). "Furthermore, NFATc1-deficient mice develop osteopetrosis due to blocked osteoclast differentiation." (PMID 33859705, 2021). "We here show that conditional knock-out RhoA in the osteoclast lineage restrains RANKL induced osteoclast formation and activity through inhibition of NFATc1 resulting in a severe osteopetrosis mouse phenotype." (PMID 37020186, 2023). "NFATc1-deleted mice developed a serious osteopetrosis due to the increasing of bone mass and failure to degrade primary spongiosa with resulting calcified cartilage accumulation." (PMID 31367247, 2019). "Reduced expression of NFATc1 leads to defects in osteoclastogenesis, and osteoclast-specific NFATc1-knockout mice develop osteopetrosis." (PMID 31540026, 2019). "Young mice with conditionally deleted Nfatc1 exhibit osteopetrosis due to impaired osteoclast differentiation." (PMID 28085946, 2017). "Moreover, NFATc1-knockout mice exhibit osteopetrosis and inhibit osteoclastogenesis in vitro and in vivo." (PMID 33671455, 2021). "As with the loss of early signaling events, the lack of either c-Fos or NFATc1 results in abolishment of osteoclast formation leading to increase bone mass and osteopetrosis in mice." (PMID 32292342, 2020). "Interestingly, p50/p52 double KO mice show severe osteopetrosis and the overexpression of NFATc1 and c-Fos rescues this phenotype, indicating a crucial role of non-canonical NF-κB signaling in RANKL-induced osteoclastogenesis." (PMID 29618833, 2018).
osteopetrosis (continued). "NFATc1 deficiency leads to the failure of the differentiation of embryonic stem cells into osteoclasts in response to RANKL, and Nfatc1 conditional knockout mice exhibit osteopetrosis." (PMID 26536233, 2015). "Conditional deletion of NFATc1 in the myeloid cell lineage results in osteoclast-poor osteopetrosis, and NFATc1-deficient osteoclast precursors fails to differentiate into osteoclasts in vitro." (PMID 25249312, 2014). "There is little conclusive evidence to show that NFATc1 plays an essential role in osteoclast function because an NFATc1 deficiency induces osteopetrosis without osteoclasts." (PMID 24465763, 2014). "Mice lacking NFκB, c‐fos and/or NFATc1 can develop osteopetrosis as they are unable to generate mature osteoclasts." (PMID 33369010, 2021). "Indeed, application of NF-κB inhibitors or deficiency in the NF-κB components p50/p52 leads to impaired NFATc1 induction, while knockout of NF-κB in mice leads to osteopetrosis due to lack of mature OCLs." (PMID 33912557, 2021). "Furthermore, on the basis of these findings, modulation of NFATc1 and IP3R2 expression and the use of calcium channel agonists may be considered for osteopetrosis therapy." (PMID 32790690, 2020). "Additionally, NF-κB p50/p52 double knockout mice display defects of osteoclast differentiation and severe osteopetrosis because c-Fos/NFATc1 was not induced by RANKL." (PMID 28567098, 2017).
pancreatic cancer (21 papers, 2011 to 2026). "Taken together, our NFATc1 gain and loss-of-function studies in six pancreatic cancer cell lines confirm the dichotomous regulation of Orai3 by NFATc1." (PMID 41023307, 2025). "Increased NFATc1 expression has also be reported to cause acinar cell trans-differentiation, initiating pancreatic cancer." (PMID 34572796, 2021). "NFATc1, a calcineurin-responsive transcription factor associated with aggressive pancreatic cancer." (PMID 24284479, 2014). "Our investigation into the mechanisms behind Orai3 protein degradation began with the observation that NFATc1 promotes Orai3 degradation in invasive and metastatic pancreatic cancer cells." (PMID 41023307, 2025). "In invasive and metastatic pancreatic cancer cells, NFATc1 induces Orai3 lysosomal degradation by transcriptionally enhancing MARCH8 E3-ubiquitin ligase." (PMID 41023307, 2025). "By harnessing the epigenetic differences in the promoter of MARCH8 E3 ubiquitin ligase, the transcription factor NFATc1 drives Orai3 transcription and protein degradation, regulating pancreatic cancer in context-dependent manner." (PMID 41023307, 2025). "We performed siRNA-mediated NFATc1 knockdown in pancreatic cancer cell lines (MiaPaCa-2, PANC-1, and CFPAC-1)." (PMID 41023307, 2025). "The bimodal regulation of Orai3 by NFATc1 in invasive and metastatic pancreatic cancer cells led to the characterization of Orai3 protein degradation machinery." (PMID 41023307, 2025). "Dichotomous control by NFATc1 defines cell state-specific roles of the Ca2+ channel Orai3 in pancreatic cancer." (PMID 41023307, 2025). "Using lysosomal and proteasomal degradation inhibitors, we observed that NFATc1 induces lysosomal degradation of Orai3 in both invasive and metastatic pancreatic cancer cells." (PMID 41023307, 2025). "Surprisingly, NFATc1 acts as a bimodal regulator in metastatic pancreatic cancer cells by inducing both Orai3 transcription and Orai3 protein degradation." (PMID 41023307, 2025). "Mechanistically, NFATc1 transcriptionally regulates MARCH8 in pancreatic cancer cells depending on the epigenetic profile of the MARCH8 promoter." (PMID 41023307, 2025). "The dual regulation of Orai3 by the same transcription factor NFATc1 underscores a complex pathway in pancreatic cancer cells that controls disease progression and clinical outcomes." (PMID 41023307, 2025). "Next, we carried out luciferase assays with NFATc1 overexpression in PANC-1 pancreatic cancer cells." (PMID 41023307, 2025). "In colon and pancreatic cancer, NFATc1 promotes cell growth by inducing the expression of c-Myc and cyclin-D." (PMID 34572796, 2021). "In order to understand the genome-wide reactions at transcript level resulting from knocking down NFATc1, we performed transcriptome profiling in the pancreatic cancer cell lines PANC-1, MiaPaCa-2 and AsPC1." (PMID 34572796, 2021). "In summary, viability, migration, and colony formation assays revealed that NFATc1 is playing an oncogenic role in pancreatic cancer cell lines." (PMID 34572796, 2021). "For instance, NFATc1 induced malignant growth phenotype in pancreatic cancer cells by upregulating MYC and promoted metastasis of mammalian cancer cells via MMP-2 upregulation." (PMID 31040921, 2019). "On the other hand, NFATc1 has been reported to be a transcriptional regulator of SOX2 in pancreatic cancer." (PMID 28737489, 2017). "Activation of NFATc1 is observed in some carcinomas such as Burkitt’s lymphoma and pancreatic cancer." (PMID 28235034, 2017). "For instance, NFATc1 induced malignant cell growth phenotype in pancreatic cancer cells by upregulating Myc and promoted metastasis of mammalian cancer cells via MMP-2 upregulation." (PMID 27259269, 2016). "We demonstrated that NFATc1 regulates DDIAS expression in both pancreatic cancer Panc-1 cells and lung cancer cells." (PMID 26740967, 2015).
pancreatic cancer (continued). "To investigate the effect of P-S on NFATc1 signaling, we generated NFATc1-knockdown cell lines from BxPC-3 and Mia PaCa-2 pancreatic cancer cells; and overexpressed NFATc1 in Mia PaCa-2 cells." (PMID 24284479, 2014). "Pharmacological inhibition of calcineurin by CsA blocks NFATc1 activation as well as its nuclear translocation; and more importantly, CsA treatment sensitizes pancreatic cancer cells to P-S." (PMID 24284479, 2014). "Next, we investigated the expression of c-myc and COX-2, target genes of NFATc1, in pancreatic cancer cells in response to P-S treatment." (PMID 24284479, 2014). "We found that when the expression of NFATc1 was abrogated by RNAi, pancreatic cancer cells were more responsive to treatment with P-S." (PMID 24284479, 2014). "P-S triggered profound upregulation of NFATc1 and its nuclear translocation in pancreatic cancer cells, leading to robust induction of its transcriptional targets, including COX-2." (PMID 24284479, 2014). "Conversely, over-expressing the NFATc1 gene made the pancreatic cancer cells less responsive to treatment with P-S." (PMID 24284479, 2014). "Given the importance of NFATc1 in pancreatic carcinogenesis and the effect of P-S in its expression, we examined its role as a modulator of the therapeutic efficacy of P-S in pancreatic cancer." (PMID 24284479, 2014). "NFATc1 has been shown to be overexpressed in pancreatic cancer and contributing to the aggressive nature of the disease." (PMID 24284479, 2014). "Buchholz and colleagues have shown that about 70% of pancreatic carcinomas have elevated levels of nuclear NFATc1 compared to healthy pancreatic tissues." (PMID 21673995, 2011). "Furthermore, NFATc1 levels were found to be significantly upregulated in spheroid-forming cells in pancreatic cancer, where NFATc1 promotes SOX2 transcriptionally." (PMID 33014880, 2020). "Activation of NFATc1 induces transcription of the c-myc gene and thereby promotes cell proliferation and anchorage-independent growth in pancreatic cancer cells, indicating that NFATc1 may play a vital role in carcinogenesis." (PMID 30534207, 2018). "In addition to their roles in influencing cell proliferation, recent studies have identified important roles for NFAT in modulating drug resistance, NFATc1 over-expression renders pancreatic cancer cells less responsive to treatment with phospho-sulindac." (PMID 28881766, 2017). "Indeed, genetic silencing of NFATc1 in pancreatic cancer cells enhanced the potency of P-S; while its ectopic expression conferred drug resistance." (PMID 24284479, 2014). "We identified NFATc1-dependent signaling as a mechanism of drug resistance in pancreatic cancer; and showed that the activation of NFATc1 is an unfavorable prognostic factor that predicts poor tumor response to P-S, which can be overcome by pharmacological intervention." (PMID 24284479, 2014). "Our findings thus provide a biochemical basis for synergism between P-S and CsA in pancreatic cancer, and suggest that the combination therapy with P-S and NFATc1 inhibitors may be a promising chemotherapeutic approach to improve treatment outcomes." (PMID 24284479, 2014). "Our study also unravels a novel role of NFATc1 in mediating drug resistance in pancreatic cancer." (PMID 24284479, 2014). "In summary, P-S induced the expression of NFATc1 in pancreatic cancer cells in vitro." (PMID 24284479, 2014). "A prime example of this is the ‘nuclear factor of activated T-cells 2’ (NFAT2 = NFATc1), whose gene regulatory activity is primarily regulated on the level of subcellular localization and which we have previously shown to be a central governor of cell growth in pancreatic cancer." (PMID 25849100, 2015).